CDK7 (cyclin dependent kinase 7)
Diseases named in the same sentence as CDK7 in open-access papers (continued):
Sharing a sentence is not in itself a finding about the gene and the disease.
prostate carcinoma (continued). "Of most interest to us, due to potential novelty for treating phenotypic plastic prostate cancer, were the cell cycle–related CDKs, which included CDK2, CDK5, and CDK7." (PMID 39113611, 2024). "Abnormal transcription activities driven by SEs, such as cyclin dependent kinase 7 (CDK7), bromodomain and extra-terminal domain (BET)/bromodomain containing 4 (BRD4), and androgen receptor (AR), have been reported to influence prostate cancer phenotypes." (PMID 38410974, 2024). "OGT O-GlcNAcylates thousands of proteins, and we use comprehensive glycoproteomic profiling to understand how depletion of CDK7 activity remodels OGT substrate repertoire in the CRPC cells and in the androgen-dependent prostate cancer cells." (PMID 36401094, 2023). "Increased sensitivity of AR-positive (compared to AR-negative) prostate cancer cell lines to THZ1, an inhibitor of CDK7/CDK12/CDK13, has been previously reported." (PMID 37076563, 2023). "CDK7 is positively regulated through complex formation with Cyclin H and MAT1, and also, these two were significantly overexpressed in prostate cancer tissue when compared to normal samples." (PMID 36401094, 2023). "Based on these data, both prostate cancer and CRPC cells can be sensitized to CDK7 inhibitors by targeting CDK9." (PMID 36401094, 2023). "In prostate cancer, SEs force the tumor cells to become addicted to dysregulated transcription programs mediated by proteins such as BRD4, CDK7, and ERG." (PMID 36408163, 2022). "In prostate cancer, SNHG1 acts as an miR-199a sponge, thus increasing the level of CDK7 (cyclin-dependent kinase 7), which stimulates cell division, and HIF-1α (hypoxia-inducible factor 1-alpha), which leads to enhanced angiogenesis." (PMID 32318335, 2020). "The oncogenic functions of CDK7 and CDK9 in prostate cancer are multifaceted." (PMID 40163908, 2025). "Next, we show that the CRPC cells, but not androgen-dependent prostate cancer cells, are sensitive to compounds targeting CDK7." (PMID 36401094, 2023). "Therefore, the use of CDK7 and CDK9 inhibitors in combination with immune checkpoint inhibitors may represent a powerful therapeutic combination, particularly for tumours displaying a “cold” immune microenvironment, as is the case of prostate cancer." (PMID 35568739, 2022). "We also highlight alternative cell cycle targets, such as CDK2 and CDK7, as well as novel combination trials that remain under investigation, in which CDK4/6 is used to modulate the biology of the prostate cancer cell rather than effect a cytostatic change." (PMID 40075623, 2025). "Strikingly, the combined inhibition of CDK7 and CDK9 led to an over 80% decrease in proliferation in the prostate cancer and CRPC cells but did not affect the cell lines derived from normal prostate epithelia." (PMID 36401094, 2023).
leukemia (20 papers, 2015 to 2025). A malignant (clonal) hematologic disorder, involving hematopoietic stem cells and characterized by the presence of primitive or atypical myeloid or lymphoid cells in the bone marrow and the blood. "Further flow cytometry and immunoblot analyses revealed that dual inhibition of BET and CDK7 caused cell cycle arrest at the G1 phase and enhanced apoptosis in both human leukemia cell lines (K562 and Jurkat) and murine BETi-resistant AF9 AML cells." (PMID 32029739, 2020). "Altogether, combining HSP90 and CDK7 targeting inhibitors can serve as a promising therapeutic combination by mitigating HSP90i-related resistance against therapy refractory leukemia." (PMID 38057328, 2023). "The anti-cancer effect of the covalent CDK7 inhibitor has been demonstrated in a variety of tumors, including leukemia, bladder cancer, glioblastoma, oesophageal squamous cell carcinoma, and osteosarcoma." (PMID 37576806, 2023). "A study published in 2022 showed that CDK7 inhibitors suppressed both leukemia stem cell (LSC)-enriched subsets in vivo and synergized with the BCL-2 inhibitor venetoclax." (PMID 36982970, 2023). "Together, results from both pharmacological inhibition and genetic depletion studies converge to support the conclusion that co-inhibition of BET and CDK7 imposes synergistic lethality against both human and rodent BETi-resistant leukemia cells in vitro." (PMID 32029739, 2020). "Collectively, we have demonstrated that co-inhibition of BET and CDK7 exerts synthetic lethality over BETi-resistant leukemia in vivo." (PMID 32029739, 2020). "RNase digestion-coupled IP and co-IP revealed a direct interaction between hnRNPK and CDK9/P-TEFb and indirect interactions between hnRNPK and CDK7/TFIIH as well as RNA-pol-II CTD-S2P in the OCI-M2 leukaemia cells." (PMID 29563491, 2018). "Given that CDK7 inhibitors kill leukemia cells, and Cn proliferation in host tissues mimics tumor-like growth, we investigated whether their utility as anticancer agents extends to antifungal activity and elucidation of CDK7 function in Cn." (PMID 41171060, 2025). "A combined BETi and CDK7 inhibitor treatment abolished MYC transcription by impeding RNAPII loading without affecting PVT1-mediated chromatin looping at the MYC locus in BETi-resistant leukemia cells." (PMID 32029739, 2020). "However, the effect of CDK7 inhibitors on the cellular metabolism of leukemia is unclear." (PMID 33889549, 2021). "Given that CDK7 inhibitors have been shown to suppress pro-oncogenic transcription by targeting enhancers in tumor cells, we envisioned that dual inhibition of BRD4 and CDK7 might synergize to suppress the growth of BETi-resistant leukemia cells to overcome resistance." (PMID 32029739, 2020). "A recent study reported that combined CDK7/12/13 inhibition with THZ1 and BRD4 inhibition overcomes enhancer reprogramming in BET inhibitor-resistant leukemia cells and consequently suppresses oncogenic transcription." (PMID 35198433, 2021). "To validate this possibility, we carried out a well-established combinatorial assay on leukemia cells with increasing doses of I-BET151 (a BRD4 inhibitor) and/or THZ1 (a CDK7 inhibitor)." (PMID 32029739, 2020). "In this study, we discovered a strong synergistic lethality of targeting the reprogrammed enhancers in BETi-resistant leukemia cells by suppressing BRD4 and CDK7 activity in vitro and in vivo." (PMID 32029739, 2020). "Although murine leukemia cells (BCR-ABL1p185+) contain high levels of CDK6, CDK7, CDK8, CDK9, and CDK19, knockdown of CDK6, CDK7, CDK9, or CDK19 has little effect on cell survival and proliferation in an inducible system." (PMID 31628323, 2019). "Remarkably, combined CDK7 and HSP90 inhibition display synergistic activity against therapy-resistant BCR-ABL1+ patient leukemia cells via blocking pro-survival HSR and HSP90α overexpression, providing a novel strategy to avoid the emergence of resistance against treatment with HSP90i alone." (PMID 38057328, 2023).
leukemia (continued). "In chronic myelogenous leukemia stem cells, suppression of super-enhancer-driven gene transcription by a CDK7 inhibitor eradicates leukemia stem cells in a mouse model without effects in normal hematopoietic stem cells." (PMID 38135679, 2023). "Taken together, these data strongly suggest that the CDK7 inhibitor can block RNAPII loading at the BETi resistance-specific PVT1 enhancer to suppress MYC transcription, thereby exerting a synergistic anticancer effect toward BETi-resistant leukemia." (PMID 32029739, 2020). "Consistent with the results from pharmacological inhibition using BETi and/or THZ1, we found that only the dual knockdown of BRD4 and CDK7, but not single-knockdown, substantially inhibited the growth of BETi-resistant leukemia cells (red/purple curves)." (PMID 32029739, 2020). "To rule out the possibility that the observed inhibitory effect might arise from off-target effects of chemicals, we knocked down BRD4 and CDK7 individually or in combination with shRNAs in both human (K562 and Jurkat) and murine AF9 leukemia cells." (PMID 32029739, 2020). "Flavopiridol is an inhibitor of cyclin-dependent kinases (CDKs) (including CDK1, CDK2, CDK4, CDK5, CDK6, CDK7, CDK8, and CDK9) and has been investigated for the treatment of several types of cancers, including leukemia, liver cancer, and renal cancer, in clinical phase 2 trials (24, –, 26)." (PMID 31822599, 2019). "Western blotting demonstrated a small increase (~1–2 fold) in the expression of total RNA-pol-II, CTD-S2P, CDK7, CDK9/P-TEFb, BRD4 and BRD2 in the 5-AZA-resistant M2AR and SCAR leukaemia cells compared to the original 5-AZA-sensitive OCI-M2 and SC leukaemia cells." (PMID 29563491, 2018). "CDK7 has been shown to play an important role in regulating the transcriptional activity of enhancers, which motivated us to test the idea that CDK7 inhibitors (e.g., THZ1) might synergize with BETi to suppress BRD4-independent enhancers to overcome BETi resistance commonly seen in leukemia." (PMID 32029739, 2020).
ovarian carcinoma (18 papers, 2009 to 2025). A malignant neoplasm originating from the surface ovarian epithelium. "Currently, SY1365, a covalent CDK7 selective inhibitor, is used in clinical trials for advanced breast and ovarian cancer (NCT03134638)." (PMID 37385987, 2023). "This is in line with previous studies highlighting the role of CDK7 in regulating ovarian cancer proliferation." (PMID 35251951, 2021). "Phosphoproteomics analyses have identified the CDK7/POLR2A axis as a new molecular node in patient-derived epithelial ovarian cancer (EOC), and it was shown that using the CDK7 inhibitor TZH1 suppressed the proliferation of EOC." (PMID 33809714, 2021). "However, in ovarian cancer cell lines, treatment with CDK7 inhibitor (THZ1) resulted in decreased expression of MECOM and decreased cell survival with no off-target effect in benign fallopian tube cell lines." (PMID 41340866, 2025). "THZ2, a small inhibitor targeted CDK7, could inhibit multiple human tumor growths including small cell lung cancer, triple-negative breast cancer, ovarian cancer." (PMID 38540292, 2024). "Similarly, studies conducted on gastric cancer, esophageal squamous cell carcinoma, and ovarian cancer showed worse survival, higher grading, and advanced tumor stages related to increased CDK7 levels." (PMID 35158760, 2022). "Additionally, an in vivo research using cell-line xenograft and EOC PDX models revealed that cyclin-dependent kinase 7 (CDK7) increased ovarian cancer weight via regulation of cell proliferation and apoptosis." (PMID 32742495, 2020). "In patient-derived xenografts models from patients with heavily pre-treated ovarian cancer, THZ1 (a chemical that inhibits CDK7, CDK12, and CDK13) repressed MYC expression and suppressed tumor growth." (PMID 33686962, 2021). "Similarly, the expression of cyclin H, MAT1, CDK7, and p-CDK2 also decreased in cyclin H silenced ovarian cancer." (PMID 32694938, 2020). "Our findings confirmed that targeting CDK7 in PDAC could effectively restrain proliferation and foster apoptosis, a pattern mirrored in T‐ALL, ovarian cancer, triple‐negative breast cancer and small‐cell lung cancer." (PMID 38037549, 2023).
triple-negative breast carcinoma (18 papers, 2016 to 2025). An invasive breast carcinoma which is negative for expression of estrogen receptor (ER), progesterone receptor (PR), and human epidermal growth factor receptor 2 (HER2). "In this vein, it was recently shown that CDK7 mediates transcriptional addiction to a vital cluster of genes associated with super-enhancers in triple-negative breast cancer (TNBC), and that TNBC cells are exceptionally dependent on CDK7." (PMID 30422115, 2018). "CDK7 expression is correlated with poor prognosis and overall survival in triple-negative breast cancer, gastric cancer, ovarian cancer, oral squamous cell carcinoma, hepatocellular carcinoma, and glioblastoma." (PMID 37342192, 2023). "Knockdown or CRISPR/Cas9-mediated knockout of CDK7 results in reduced cell proliferation of gastric cancer and triple-negative breast cancer cells, respectively, highlighting a functional role of CDK7 in tumor cell growth." (PMID 35054996, 2022). "Here, the possible mechanism of CDK7 inhibitors for treating human triple-negative breast cancer (TNBC) has been studied." (PMID 34109118, 2021). "Previous studies have reported that high CDK7 expression, together with Cyclin H and MAT1, was associated with better prognosis in ER-positive breast cancer patients and worse prognosis in triple negative breast cancer patients." (PMID 32155786, 2020). "Recent studies using kinase inhibitors and gene editing demonstrated that triple-negative breast cancer cells are transcriptional dependent on CDK7." (PMID 28423697, 2017). "Cancer studies on CDK7 gained momentum upon discovery of the covalently binding inhibitor THZ1 that blocks growth of various cancer entities, among them triple negative breast cancer, Myc-associated tumors, non-small cell lung carcinoma and also pancreatic cancer." (PMID 35054996, 2022). "Moreover, triple-negative breast cancer cells are reported to be highly addicted to CDK7-dependent transcription, implying the inhibition of CDK7 as a therapeutic target." (PMID 34298635, 2021). "Triple-negative breast cancer (TNBC) cells are exceptionally dependent on CDK7, and a vital cluster of genes in TNBC is especially sensitive to CDK7 inhibition." (PMID 33686962, 2021). "Cancer cells are addicted to transcription driven by SEs and thus highly dependent on CDK7 activity, as exemplified by the identification of a so-called “Achilles cluster” of genes in MYCN amplified glioblastoma, triple-negative breast cancer, and pancreatic cancer." (PMID 37385987, 2023). "Additionally, we observed that THZ2 reduces SOX9 protein levels in GBM cells, suggesting that CDK7 inhibition may enhance TMZ sensitivity by suppressing SOX9 expression, similar to its role in triple-negative breast cancer." (PMID 40843352, 2025).
small cell lung carcinoma (14 papers, 2016 to 2025). Small cell lung cancer (SCLC) is a highly aggressive malignant neoplasm, accounting for 10-15% of lung cancer cases, characterized byrapid growth, and early metastasis. "Concerning lung cancer, THZ1, a selective CDK7 covalent inhibitor, has recently been shown to be effective in reducing the expression of superenhancer-associated genes and inhibiting growth of small cell lung cancer (SCLC)." (PMID 36212402, 2022). "More recently, THZ1, a selective CDK7 covalent inhibitor, has been shown to be effective in reducing the expression of super-enhancer associated genes and inhibiting the growth of multiple cancers such as small cell lung cancer, MYCN-driven neuroblastoma cells, and triple-negative breast cancer." (PMID 32690037, 2020). "Secondly, in addition to suppressing cell proliferation, CDK7 inhibition by YLK-5-124 was found to induce interferon gamma signalling along with other inflammatory response pathways in models of small cell lung cancer." (PMID 37076563, 2023). "Consistently, CDK7 inhibition by YKL-5-124 has been shown to elicit genomic instability in small cell lung cancer models, while CDK12/13 inhibition has been shown to provoke a “BRCA-ness” phenotype in TNBC." (PMID 35568739, 2022). "In line with this, the genomic instability induced by CDK7 inhibition in small cell lung cancer models activated antitumour T-cells, eliciting a robust immune surveillance program which improved the efficacy of anti-PD-1 therapy." (PMID 35568739, 2022). "Formation of a stable dimer of CDK7/cyclin H requires phosphorylation on a conserved threonine (Thr170) in the activation loop of CDK7 and is essential for activity (human cervical tumor cell line–HeLa; human lung small cell carcinoma cell line–H1299; insect cells–SF9)." (PMID 33805800, 2021). "Moreover, small cell lung cancer research revealed that the CDK7 inhibitor YKL-5-124 activated CXCL9 and that CXCL10 signalling may be a promising outcome of combining YKL-5-124 and anti-PD-1, confirming the pivotal function of CXCL9 in immunotherapy." (PMID 34527583, 2021). "YKL-5-124, a potent CDK7 inhibitor, activates IFN-γ signaling and induces TNF-a and CXCL9/10 in small-cell lung cancer." (PMID 40175357, 2025). "Inhibition of CDK7 was demonstrated using the selective CDK7 inhibitor YKL-5-124 to predominantly disrupt cell cycle progression and induce DNA replication stress and genomic instability in small cell lung cancer, while triggering immune response signaling." (PMID 38540292, 2024). "For instance, CDK7 inhibition by a small inhibitor YKL-5-124 induces DNA replication stress, genome instability and a robust immune surveillance program elicited by T cells, thus a combination of YKL-5-124 and anti-PD-1 shows evident survival benefit in small cell lung cancer." (PMID 40175357, 2025).
glioblastoma (12 papers, 2013 to 2026). The most malignant astrocytic tumor (WHO grade IV). "Associations between CDK7 and reduced survival have been observed in gastric cancer, ovarian cancer, oral squamous cell carcinoma, hepatocellular carcinoma, and glioblastoma." (PMID 39800748, 2025). "A recent study conducted on a human glioblastoma cell line showed that protein kinase C- (PKC-) ι phosphorylates CDK7 at Thr170 and CDK2 at Thr160." (PMID 23840966, 2013). "Indeed, the phosphorylation of Serine 5 on the CTD of the RNAPII is reduced by flavopiridol via its inhibitory effect on CDK7 in human glioblastoma cells." (PMID 27715402, 2016). "Furthermore, flavopiridol, a CDK7/9 inhibitor, caused substantial phosphorylation of AKT in human glioblastoma cells, indicating that inhibition of CDKs might result in PI3K-AKT pathway activation, which may lead to cell survival or protection from apoptosis." (PMID 37537243, 2023). "Cyclin dependent kinase 7 (CDK7) is frequently overexpressed in various malignancies, including glioblastoma (GBM), where elevated expression correlates with poor prognosis." (PMID 40836584, 2025). "A total of 5 key DNA repair genes, CDK7, DDB2, RNH1, RFC2 and FAH, were screened to be significantly related to the prognosis of glioblastomas (p = 9.74e−05)." (PMID 28938550, 2017). "This study was conducted on human glioblastoma and human prostate cancer cell lines and utilized siRNA molecules for the silencing of CDK9- and/or CDK7-related pathways." (PMID 23840966, 2013). "Here we find that glioblastoma stem cells (GSCs) are selectively sensitive to CDK12/CDK13 inhibition, whereas CDK7 and CDK9 inhibition cause non-specific cytotoxicity." (PMID 41882177, 2026). "PIK3CG, SRC, AURKA, CDK7, and PLAT might be key molecular targets of plinabulin in glioblastoma." (PMID 39877641, 2025).